ICAM1 (intercellular adhesion molecule 1)
Diseases named in the same sentence as ICAM1 in open-access papers (continued):
Sharing a sentence is not in itself a finding about the gene and the disease.
Ewing sarcoma (3 papers, 2019 to 2023). A small round cell tumor that lacks morphologic, immunohistochemical, and electron microscopic evidence of neuroectodermal differentiation. "Together, these results indicate that USP6 expression in Ewing sarcoma cells directly activates NK cells by enhancing both immune synapse formation (via ICAM-1) as well as degranulation via multiple NK cell-activating ligands." (PMID 37615015, 2023). "To determine if IFN-γ contributes to the increased ICAM-1 expression noted in the Ewing tumor cells following T-cell co-culture, we tested the effect of neutralizing IFN-γ using a blocking antibody." (PMID 31164960, 2019). "We found that IFN-γ blocking antibody blunts the early T-cell mediated increases in Ewing tumor cell ICAM-1 expression in both A673 and CHLA10 cells." (PMID 31164960, 2019). "Following co-culture, T-cells were washed away and Ewing tumor cells were then analyzed for ICAM-1 expression." (PMID 31164960, 2019). "The percentage of ICAM-1 expressing Ewing tumor cells we noted in culture is in line with values reported from prior studies." (PMID 31164960, 2019). "We next sought to determine the mechanism by which T-cells induce ICAM-1 expression in co-cultured Ewing tumor cells." (PMID 31164960, 2019). "We also examined the effect of directly treating Ewing tumor cells with IFN-γ on tumor cell ICAM-1 expression." (PMID 31164960, 2019). "Indeed, treatment of Ewing sarcoma cells with recombinant IFN-γ leads to a significant increase in ICAM-1 expression in the majority of cells." (PMID 31164960, 2019). "Since several cancers have been shown to upregulate ICAM-1 expression after exposure to T-cells, we tested whether this was also the case for Ewing tumor cells." (PMID 31164960, 2019). "We have thus far established that: 1) IFN-γ induces ICAM-1 expression in Ewing sarcoma cells and that 2) Ewing cell EWS-FLI1 level dictates the magnitude of ICAM-1 transcriptional response to IFN-γ, with greater IFN-γ mediated ICAM-1 induction in cells with lower EWS-FLI1." (PMID 31164960, 2019). "Differences in ICAM-1 expression between Ewing cells with high and low EWS-FLI1 may suggest that these sub-populations of Ewing tumor cells could possess innate differences in their ability to engage T-cells." (PMID 31164960, 2019).
Fabry disease (3 papers, 2013 to 2024). Fabry disease (FD) is a progressive, inherited, multisystemic lysosomal storage disease characterized by specific neurological, cutaneous, renal, cardiovascular, cochleo-vestibular and cerebrovascular manifestations. "In the context of Fabry disease, elevated levels of adhesion molecules such as VLA4, CR3, ICAM1, VCAM1, and PECAM1 in the bloodstream are closely linked to disease severity." (PMID 39596318, 2024). "In Fabry disease, elevated levels of ICAM1, VCAM1, and PECAM1 have been observed in peripheral blood cells." (PMID 39596318, 2024). "In patients with Fabry disease, a significant increase in the expression of CD18, the β subunit of LFA1, on peripheral monocytes has been observed, along with elevated levels of ICAM1 in the bloodstream." (PMID 39596318, 2024). "Another study indicates that excess Gb3 on exposed endothelial cells leads to the upregulation of adhesion molecules like ICAM1 and VCAM1 in Fabry disease." (PMID 39596318, 2024). "In addition, circulating monocytes in Fabry disease show upregulation of MHC II expression, alongside significantly elevated levels of soluble ICAM 1 and VCAM1." (PMID 39596318, 2024). "Moreover, Gb3 upregulates VCAM-1 (Vascular cell adhesion protein 1) but not ICAM-1 (Intercellular Adhesion Molecule 1) expression in HMiVECs, indicating a pro-inflammatory phenotype in Fabry disease." (PMID 39125842, 2024).
Fever (3 papers, 2017 to 2022). Body temperature elevated above the normal range. "The results demonstrated that the levels of ET-1, ICAM-1, TNF-α, IL-1β, MMP-9, NF-κB, NO, and TXB2 in yeast-induced fever in the model group rats were significantly higher than in the control group (P < 0.001)." (PMID 35178159, 2022).
fungal infection (3 papers, 2018 to 2024). "We found that MCs activation initiated by fungi infection contributed to the neutrophil infiltration by influencing the expression of ICAM-1 to the infected cornea and result in protection in FK." (PMID 29849098, 2018). "Additionally, other studies have found that hyperferritinemia and elevated plasma levels of adhesion molecules such as soluble intercellular adhesion molecule-1 (sICAM-1), thrombospondin-1, and vinculin promote invasive fungal infections." (PMID 39176311, 2024).
graft versus host disease (3 papers, 2020 to 2025). An immune system disorder that occurs after allogeneic hematopoietic stem cell transplant and is a reaction of donor immune cells against host tissues. "ICAM-1 also has immunosuppressive effects on dendritic cells and T cells, which may aid in the treatment of graft versus host diseases." (PMID 32054483, 2020). "In a murine model of graft-versus-host disease (GVHD), an infusion of ICAM-1+ BM-MSCs reduced the expression of inflammatory cytokines and the percentage of Th1 lymphocytes." (PMID 34502453, 2021).
Hashimoto thyroiditis (3 papers, 2016 to 2025). An autoimmune disorder caused by the production of autoantibodies against thyroid tissue. "Furthermore, significant reduction in ICAM-1 levels occurred after N. sativa oil consumption in two clinical trials involving type 2 diabetic and CAD patients, whilst no significant change was noticed in subjects with the risk factor for CVD and Hashimoto’s thyroiditis patients." (PMID 40365513, 2025). "Also, Abbasalizad Farhangi and Tajmiri26 reported that consuming 2 g/day N. sativa powder for 8 weeks caused significant decrease in serum VCAM-1 levels, whereas did not significantly alter serum ICAM-1 levels in Hashimoto’s thyroiditis patients compared with the controls." (PMID 40365513, 2025).
hematoma (3 papers, 2016 to 2024). A hematoma is a collection of blood from a vascular structure into an extravascular space. "In our study, neutrophils infiltrated into brain and promoted the mRNA transcription of CCL2 (also referred to as MCP-1), ICAM-1 and pro-inflammatory factors around hematoma." (PMID 30631264, 2018). "In the S1P-treated mice, we found that the levels of ICAM-1 protein and mRNA in the lung fractions, the pulmonary hematoma and leukocyte count in bronchoalveolar lavage fluid were enhanced through a PKCδ/PYK2/NADPH oxidase/ROS/NF-κB signaling pathway." (PMID 27065868, 2016). "On day 1 after ICH, the expression of VCAM‐1, ICAM‐1, and PECAM‐1 were significantly up regulated in the peri‐hematoma region when compared to the sham group." (PMID 38044319, 2024).
hyperhomocysteinemia (3 papers, 2017 to 2021). A serious metabolic condition caused by mutations in the MTHFR gene, medications, or nutritional deficiency. "An increased plasma intercellular adhesion molecule 1 (ICAM-1) and serum amyloid A (S-AA) in patients with high plasma tHcy suggest an association between hyperhomocysteinemia and low-grade inflammation." (PMID 34786033, 2021). "Specifically, the endothelial adherence by neutrophils upon hyperhomocysteinemia is accelerated by upregulating the P-selectin, L-selectin, intercellular adhesion molecule-1 (ICAM-1), and CD11b/CD18." (PMID 28938553, 2017). "Additionally, caffeic acid was seen to reduce the expression of adhesion molecules such as E-selectin and ICAM-1 on endothelium and integrin CD11b/CD18 (Mac-1 (macrophage-1 antigen)) on leukocytes caused by hyperhomocysteinemia." (PMID 28335422, 2017).
hypertriglyceridemia (3 papers, 2013 to 2023). A laboratory test result indicating elevated triglyceride concentration in the blood. "While the size of the VLDL particle was not linked to ICAM-1 concentrations, all VLDL subclasses were positively associated with ICAM-1 concentration, underlining the potential proinflammatory and proatherogenic implications of hypertriglyceridemia." (PMID 23940575, 2013). "The previous report showed the levels of soluble E-selectin, soluble ICAM-1, and soluble VCAM-1 in the serum of patients with hypertriglyceridemia were increased, and multivariable analyses revealed that this increase was independent of other risk factors." (PMID 31550292, 2019).
IgA nephropathy (3 papers, 2022). "Accordingly, the tubulointerstitial expression of ICAM1 has been suggested as a marker of injury in IgA nephropathy." (PMID 35806457, 2022). "Based on our analysis, ICAM1 is found upregulated in microarrays from kidneys of patients with CKD, focal segmental glomerulosclerosis, and IgA nephropathy compared to controls, thus underscoring its importance in all these situations." (PMID 35806457, 2022). "ICAM-1 is involved in renal tubulointerstitial injury; however, the expression and clinical implication of ICR are not determined in IgA nephropathy (IgAN)." (PMID 35688937, 2022).
interstitial lung disease (3 papers, 2023 to 2025). A diverse group of lung diseases that affect the lung parenchyma. "In recent years, successful new candidate serum biomarkers have been identified for SSc-associated interstitial lung disease (ILD), including surfactant protein D (SP-D), Krebs von den Lungen 6 glycoprotein (KL-6), CCL18 and intercellular adhesion molecule 1 (ICAM-1)." (PMID 39156689, 2024).
intestinal inflammation (3 papers, 2015 to 2024). "Additionally, studies have found that blocking ICAM-1 and VCAM-1 can reduce leukocyte adhesion in rat ileitis, indicating their potential in the treatment of intestinal inflammation." (PMID 38660311, 2024).
leprosy (3 papers, 2007 to 2018). Leprosy is a chronic infectious disease affecting primarily the skin and peripheral nervous system. "Keratinocytes expressing ICAM-1 are found in lesions from leprosy patients that present strong cellular immune response against M. leprae (tuberculoid, reversal reaction), but not in lepromatous lesions." (PMID 29643852, 2018). "PCR analysis demonstrated the expression of inflammatory cytokines TNF, IL-6, and IL-12 besides high expression of ICAM-1 in the epidermis of reactional leprosy lesions." (PMID 29643852, 2018). "The number and distribution of CD1a+ skin cells and HLA-DR and intercellular adhesion molecule (ICAM)-1 expression were analysed in leprosy skin lesions and in delayed-type hypersensitivity (DTH) tests." (PMID 17927586, 2007).
non-alcoholic fatty liver disease (3 papers, 2019 to 2023). "Aucubin also prevented the elevation of MMP-9, MCP-1, apoC-III, ICAM-1, VCAM-1, TNF-α, IL-1β, and IL-6 levels after stimulation by apoC-III in 3T3-L1 cells and in mice with tyloxapol-induced nonalcoholic fatty liver disease (NAFLD)." (PMID 37241895, 2023).
ovarian adenocarcinoma (3 papers, 2001 to 2019). An adenocarcinoma that arises from the ovary. "Further investigation revealed ICAM-1 was expressed in the surface epithelium of normal ovaries and both mRNA and protein expression levels were reduced in the majority of ovarian adenocarcinoma cell lines and primary tumours." (PMID 11720474, 2001).
pancreatic adenocarcinoma (3 papers, 2013 to 2023). "Moreover, high expression of ICAM1 and high expression of ADAM10 or ADAM17 was associated with poor clinical outcome in pancreatic adenocarcinoma patients." (PMID 37732732, 2023).
Pleural effusion (3 papers, 1996 to 2025). The presence of an excessive amount of fluid in the pleural cavity. "In pleural fluid, levels of s.VCAM-1 and s.ICAM-1 were increased in pleural effusions." (PMID 18475740, 1996). "Up-regulation of s.VCAM-1 and s.ICAM-1 in serum, along with increased levels of sE-selectin in pleural effusions from tuberculous patients, may result in transmigration of activated inflammatory cells inducing pleural damage, which may contribute to the pathological processes involved." (PMID 18475740, 1996). "Additionally, PMCs derived from transudative pleural effusion expressed lower levels of ICAM-1 and VCAM-1 than TPE derived-PMCs, though it was not statistically significant." (PMID 24069325, 2013).
pterygium (3 papers, 2013 to 2023). A wedge-shaped fibrovascular lesion arising from the bulbar conjunctiva and extending to the cornea. "Several DEGs in pterygium and pSS tissues were identified from the datasets, and five hub genes (IL1R1, ICAM1, IRAK1, S100A9, and S100A8) were finally screened out." (PMID 36768371, 2023). "Compared with the healthy control conjunctiva, the expression of five hub genes (IL1R1, ICAM1, IRAK1, S100A9, and S100A8) in pterygium or pSS samples was statistically significant (p < 0.05)." (PMID 36768371, 2023). "We identified a shared gene signature (IL1R1, ICAM1, IRAK1, S100A9, and S100A8) between pterygium presence and pSS." (PMID 36768371, 2023).
rectal cancer (3 papers, 2016 to 2021). A primary or metastatic malignant neoplasm that affects the rectum. "Expression of CD80 on DCs treated with TCM from irradiated rectal cancer tissue correlated with levels of ICAM-1 (r = 0.8214, p = 0.03) and CD11c correlated with IL-1RA (r = 0.7619, p = 0.03)." (PMID 33540635, 2021). "In the irradiated rectal cancer, TME CD80 correlated with ICAM-1 and CD11c correlated with IL-1RA." (PMID 33540635, 2021).
rhabdomyosarcoma (3 papers, 2012 to 2021). A rare aggressive malignant mesenchymal neoplasm arising from skeletal muscle. "Entry and infection of the HSPG-binding variant of HRV8 (HRV8v) in rhabdomyosarcoma cells devoid of ICAM-1 were very similar to entry and infection of HRV14 in these cells." (PMID 23227049, 2012). "Similar tubules filled with intercellular adhesion molecule 1 (ICAM-1)-binding rhinoviruses had been observed in rhabdomyosarcoma cells overexpressing this receptor." (PMID 27174165, 2016). "In HeLa cells, HRV14 uptake occurs by a dynamin- and presumably clathrin-dependent route, whereas endocytosis in ICAM-1 overexpressing rhabdomyosarcoma cells is independent of clathrin, caveolin, flotillin, and lipid rafts." (PMID 23227049, 2012).
schistosomiasis (3 papers, 2011 to 2024). An infectious disease caused by parasitic trematodes of the genus Schistosoma that colonize human blood vessels and release eggs that can cause granulomatous reactions leading to acute (swimmer's itch or acute schistosomiasis syndrome) or chronic disease. "For instance, in schistosomiasis there is an increase in the plasma concentration of soluble intercellular adhesion molecule (ICAM)-1, a classical marker of endothelial activation in inflammation, which correlates to the severity of the disease." (PMID 21853150, 2011). "In this context, in schistosomiasis, there is an increase in the expression of ICAM-1 and plasma soluble ICAM-1, a marker of inflammatory diseases and endothelial activation." (PMID 21853150, 2011). "In good accordance, previous data showed that PDTC inhibits VCAM-1, but not ICAM-1, expression and highlighted the role of VCAM-1 in schistosomiasis pathogenesis." (PMID 38239348, 2023).
sickle cell disease (3 papers, 2013 to 2022). Sickle cell anemias are chronic hemolytic diseases that may induce three types of acute accidents: severe anemia, severe bacterial infections, and ischemic vasoocclusive accidents (VOA) caused by sickle-shaped red blood cells obstructing small blood vessels and capillaries. "Furthermore, consistent with previous reports suggesting an up-regulation of inflammatory pathways in sickle cell disease vs. controls, we found significantly greater concentrations of the inflammatory cytokine TNF-α, but not IL-1β or the adhesion molecule, ICAM-1 in the sickle cell disease group." (PMID 23922670, 2013).
skin cancer (3 papers, 2008 to 2026). "We have previously shown that ICAM-1 expression is associated with the skin cancer risk in cells from patients with XP." (PMID 21566739, 2008). "Also, the available data suggest that the expression of ICAM-1 and VCAM-1 in fibroblasts, which are generally absent or low, can be upregulated by inflammatory cytokines, raising the question of their possible role in tumorigenesis and tumor spread in skin cancers." (PMID 41597444, 2026).
spinal cord injury (3 papers, 2018 to 2019). Penetrating and non-penetrating injuries to the spinal cord resulting from traumatic external forces (e.g., WOUNDS, GUNSHOT; WHIPLASH INJURIES; etc.). "CD11b is a natural ligand for ICAM-1, a key molecule in the adhesion and extravasation of leukocytes through activated vascular endothelium following spinal cord injury." (PMID 29548992, 2018).
staphylococcus aureus infection (3 papers, 2018 to 2023). An infectious process in which the bacteria Staphylococcus aureus is present. "Among which, we also performed the PPI network of several DEGS including C3, HLA-DRB5, ICAM1 and HLA-DRB1, ITGAM, and CFD that involved in the staphylococcus aureus infection signaling pathway." (PMID 30186855, 2018).
synovitis (3 papers, 2018 to 2024). Inflammation of a synovial membrane. "Then they discovered that the expression of intercellular adhesion molecule 1 (ICAM-1) and vascular cell adhesion molecule 1 (VCAM-1), two factors in synovitis, were downregulated after the clodronate liposomes treatment, further confirming the anti-inflammation effect via macrophage depletion." (PMID 36032667, 2022).
urticaria (3 papers, 2024). A vascular reaction of the skin characterized by erythema and wheal formation due to localized increase of vascular permeability. "There is limited recent primary research investigating the role of VCAM-1 and ICAM-1 in urticaria, both in vivo and in vitro." (PMID 38671667, 2024). "We focused on VCAM-1 and ICAM-1, but parallel investigation of other possible biomarkers, which were not considered in this study, and their interplay in the pathophysiology of urticaria could contribute to a more comprehensive understanding." (PMID 38671667, 2024). "The primary objective of this study was to determine whether the two biological indices, VCAM-1 and ICAM-1, sampled from groups of children with urticaria, returned to normal levels after treatment." (PMID 38671667, 2024). "In most cases, FEX significantly decreased the expression of Intercellular Adhesion Molecule-1 (ICAM-1) and Endothelial Leukocyte Adhesion Molecule-1 (ELAM-1) on endothelial cells (p < 0.05), decreased the expression of tryptase and some adhesion molecules in urticaria sufferers." (PMID 39252789, 2024).
uveal melanoma (3 papers, 2008 to 2019). A melanoma derived from melanocytes of the uveal tract. "Recent work based on the use of a mouse antibody against ICAM-1 has shown that blocking this adhesion molecule inhibits the growth of uveal melanoma in a severe combined immunideficient (SCID) mouse model." (PMID 18958307, 2008). "Finally, Mel202/DR1/CD80 uveal melanoma vaccine cells expressed the intercellular adhesion molecule 1 (ICAM-1) that was pivotal for CD4+ T cell activation via lymphocyte function-associated antigen 1(LFA-1)." (PMID 30956760, 2019). "Therefore, the ICAM-1/LFA-1 interaction plays an important role in the activation of CD4+ T cells by Mel202/DR1/CD80 uveal melanoma vaccines." (PMID 30956760, 2019).
vascular occlusion (3 papers, 2013 to 2022). "After vascular occlusion, IL-1 and IL-6 expression increases, and they act on vascular endothelial cells to express ICAM-1 and selectins, causing leukocyte aggregation and adhesion, and mediating the inflammatory cascade to worsen cerebral ischemic injury." (PMID 36145501, 2022). "After vascular occlusion, the upregulation of cytokines including IL-1 and IL-6 promotes the expression of ICAM-1, P-selectin, and E-selectin in the vascular endothelium, and these inflammatory signals further promote vascular endothelium dysfunction." (PMID 26024305, 2015).